COX4I1P1 (cytochrome c oxidase subunit 4I1 pseudogene 1)
Synonyms: formerly COX4P1; COX4L1
Gene: Processed pseudogene on chromosome 14 (61,831,861 to 61,832,369, reverse strand). Ensembl gene ENSG00000258956.
Diseases named in the same sentence as COX4I1P1 in open-access papers:
COX4I1P1 is named in the same sentence as 2 diseases in open-access papers, as found by Europe PMC text mining. Sharing a sentence is not in itself a finding about the gene and the disease.
COX4I1P1 shares sentences with these, for which no sentence is quoted: glioma (1 paper); tumor (1).